TRIM14 (tripartite motif containing 14)
Diseases named in the same sentence as TRIM14 in open-access papers (continued):
Sharing a sentence is not in itself a finding about the gene and the disease.
colon cancer (3 papers, 2022 to 2024). "ELFN1-AS1 is upregulated in colon cancer cells via hypoxia-induced upregulation, and it competitively and endogenously binds to miR-191-5p to upregulate the tripartite motif TRIM 14 (TRIM14) to promote colon cancer growth and metastasis." (PMID 38002356, 2023). "In conclusion, ELFN1-AS1 operates as a downstream target of hypoxia, promotes proliferation and invasion, and inhibits apoptosis through upregulating TRIM14 by sponging miR-191-5p in the colon cancer cells." (PMID 35652045, 2022). "In our research, we clarified that hypoxia promoted the growth and metastasis of tumor cells by upregulating the ELFN1-AS1/miR-191-5p/tripartite motif 14 (TRIM14) axis, providing potential targets for the clinical treatment of colon cancer." (PMID 35652045, 2022). "In conclusion, ELFN1-AS1 operates as a downstream target of hypoxia to promote proliferation and invasion through upregulating TRIM14 by sponging miR-191-5p in colon cancer cells." (PMID 35652045, 2022). "Importantly, the mRNA level of TRIM14 was significantly upregulated in 32 colon cancer tissues compared with para-cancerous tissues." (PMID 35652045, 2022). "Five TRIM expression was significantly upregulated (TRIM14, TRIM15, TRIM24, TRIM29, and TRIM31), and the other five TRIM genes showed decreased expression (TRIM1, TRIM3, TRIM9, TRIM22, and TRIM73) in both colon cancer (COAD) and rectal cancer (READ)." (PMID 38769340, 2024). "TRIM14 rescues the inhibition of the proliferation and invasion induced by ELFN1-AS1 knockdown in colon cancer cells." (PMID 35652045, 2022).
non-small cell lung carcinoma (3 papers, 2017 to 2021). A group of at least three distinct histological types of lung cancer, including non-small cell squamous cell carcinoma, adenocarcinoma, and large cell carcinoma. "However, in non-small cell lung cancer, TRIM14 was downregulated and functioned as a tumor suppressor to block tumor cells proliferation." (PMID 33982666, 2021).
papillary thyroid carcinoma (3 papers, 2021 to 2022). "Some other studies showed that miR-4443 can inhibit metastasis and energy metabolism of papillary thyroid cancer through targeting TRIM14." (PMID 36204659, 2022). "Furthermore, TRIM14 promoted papillary thyroid carcinoma cell proliferation via the interaction with SOCS1, a negative regulator of the STAT3 activation." (PMID 33982666, 2021). "Moreover, the inhibition of TRIM14 could decrease the proliferation of papillary thyroid carcinoma." (PMID 34656078, 2021).
tongue cancer (3 papers, 2016 to 2022). A malignant neoplasm affecting the tongue. "In this current study, we reported that TRIM14 expression was significantly upregulated in tongue cancer cells and clinical tissues, and was associated with the clinical features of tongue cancer." (PMID 26799420, 2016). "Promotes DDP resistance of tongue cancer by sponging miR-124-30 to regulate TRIM14 expression.Facilitates tumor growth and chemo-resistance by acting as a competing endogenous RNA (ceRNA) to modulate the expression of miR-211-5p." (PMID 35978835, 2022).
atherosclerosis (2 papers, 2021 to 2025). A disease characterized by the build-up of fatty material and calcium deposition in the arterial wall resulting in partial or complete occlusion of the arterial lumen. "Up-regulation of TRIM14 acts on miR-330-5p via circIRAK1 to cause oxidized-LDL-induced endothelial cell injury in atherosclerosis." (PMID 40835966, 2025).
colitis (2 papers, 2020). Inflammation of the colon. "The broad functional impact of this regulation is implicated by the results from TRIM14 knockout mice that exhibit impaired NF–κB triggered inflammation, as well as colitis and colitis-associated tumor development." (PMID 33066016, 2020). "Remarkably, when compared with WT mice, both Trim14−/− chimera mice and NFκb2‐KD chimera mice were considerably more resistant to DSS‐induced acute colitis in both overall survival, weight loss, and colon length." (PMID 31921549, 2020). "TRIM14 deficiency in mice significantly impairs noncanonical NF‐κB‐mediated inflammatory responses as well as acute colitis and colitis‐associated colon cancer development." (PMID 31921549, 2020).
lung adenocarcinoma (2 papers, 2017 to 2018). A carcinoma that arises from the lung and is characterized by the presence of malignant glandular epithelial cells. "miR-15b had a dual role in oral tongue squamous cell carcinoma (TSCC) and lung adenocarcinoma; through the regulation of TRIM14 it was implicated in the reversion of cisplatin resistance in TSCC, while it decreased sensitivity to cisplatin by targeting PEBP4 in lung adenocarcinoma." (PMID 30211115, 2018).
lung carcinoma (2 papers, 2017 to 2019). "In order to identify the role of TRIM14 in controlling IAV infection, we first analyzed TRIM14 expression in human lung carcinoma cell line A549 infected with IAV or stimulated with type-I or II interferon." (PMID 30873142, 2019). "In conclusion, our findings provide the first in vitro and in vivo evidence that TRIM14 has a tumor suppressive role in lung cancer." (PMID 28059079, 2017). "Here, we have combined a genetic screen, clinical data, functional assays and in vivo xenograft models to provide strong evidence that TRIM14 plays a novel tumor-suppressive role in lung cancer." (PMID 28059079, 2017). "Here we report the first demonstration of tumor suppressive activity and immune regulation of TRIM14 in lung cancer cells." (PMID 28059079, 2017). "Here we demonstrated for the first time that TRIM14 positively regulates type II IFN signaling in lung cancer cells." (PMID 28059079, 2017). "To validate the functional role of TRIM14 as a putative tumor suppressor gene (TSG) in lung cancer, we first screened TRIM14 protein expression using Western blot analysis in twelve different NSCLC cell lines and an immortalized but non-tumorigenic human bronchial epithelial cell line (HBE135)." (PMID 28059079, 2017). "Here, we demonstrate for the first time that p62 (SQSTM1) immunoprecipitates with TRIM14 in both HEK293T and H1395 lung cancer cells." (PMID 28059079, 2017).
lymphoma (2 papers, 2017 to 2025). A malignant (clonal) proliferation of B- lymphocytes or T- lymphocytes which involves the lymph nodes, bone marrow and/or extranodal sites. "TRIM14, initially recognized as KIAA0129, was first detected as being overexpressed in HIV-infected human and simian lymphomas through subtractive hybridization techniques." (PMID 40435148, 2025).
non-Hodgkin lymphoma (2 papers, 2021 to 2022). Distinct from Hodgkin lymphoma both morphologically and biologically, non-Hodgkin lymphoma (NHL) is characterized by the absence of Reed-Sternberg cells, can occur at any age, and usually presents as a localized or generalized lymphadenopathy associated with fever and weight loss. "A previous report revealed that TRIM14 was highly expressed in a human immunodeficiency virus-related non-Hodgkin's lymphoma." (PMID 35962353, 2022). "TRIM14 was originally known as KIAA0129, and its overexpression was first found in human immunodeficiency virus- (HIV-) infected human and simian non-Hodgkin's lymphoma infected with simian immunodeficiency virus (SIV)." (PMID 34712740, 2021).
squamous carcinoma (2 papers, 2017 to 2019). "TRIM14 expression did not correlate with survival in the University of Michigan study, which included only squamous carcinoma patients (HR = 1.17, 95% CI = 0.48–2.83, p = 0.733)." (PMID 28059079, 2017).
cardiac hypertrophy (1 paper, 2024). "Furthermore, in the heart, the overexpression of TRIM14 promotes cardiomyocyte hypertrophy and fibrosis and positively regulates stress-load-induced cardiac hypertrophy and cardiac insufficiency, possibly through the activation of the AKT signaling pathway by TRIM14." (PMID 39719450, 2024).
Cerebral ischemia (1 paper, 2025). Restriction of arterial blood supply to the brain associated with insufficient oxygenation to support the metabolic requirements of the tissue. "Given the shared neuroinflammatory mechanisms between SCI and cerebral ischemia, we hypothesized that TRIM14 may similarly play a pivotal role in SCI pathogenesis." (PMID 41250673, 2025).
cervical spondylosis (1 paper, 2024). "In this paper, we will describe the structure of TRIM14, review its role in cancer, cardiovascular disease, cervical spondylosis, inflammation and antiviral immunity, and provide an outlook on future research directions." (PMID 39719450, 2024).
chronic periodontitis (1 paper, 2024). A chronic inflammatory process that affects the tissues that surround and support the teeth. "In chronic periodontitis, it has been reported that TRIM14 deficiency leads to decreased osteoclast formation and p100 and p52 expression, which in turn inhibits atypical NF-κB signaling pathway activation, thereby preventing bone loss and destruction during chronic periodontitis." (PMID 39719450, 2024). "Therefore, targeting TRIM14 may be an effective treatment for preventing chronic periodontitis." (PMID 39719450, 2024).
colon disease (1 paper, 2020). "To further confirm whether the function of TRIM14 in colon disease is through the decrease of p100/p52 protein level, we performed DSS‐induced acute colitis in WT, Trim14−/−, and NFκb2‐knockdown (KD) chimera mice." (PMID 31921549, 2020).
COVID-19 (1 paper, 2021). A disease caused by infection with severe acute respiratory syndrome coronavirus 2. "Of these, nine ISGs were differentially regulated in Asymptomatic versus mild COVID-19 cases; IFNAR2, IRF2BP1, IRF4, MAVS, and TRIM14 were upregulated; whilst IRF2BP2, IRF2BPL, and SOCS3 were downregulated." (PMID 34824360, 2021).
Flavivirus Infections (1 paper, 2025). Infections with viruses of the genus FLAVIVIRUS, family FLAVIVIRIDAE. "Altogether, these data suggest that TRIM38, TRIM21, and TRIM14 are ISGs that mediate the IFN-I response against flavivirus infection." (PMID 40431659, 2025). "From the screening, we identified the TRIM38, TRIM21, and TRIM14 proteins, which were enriched during flavivirus infection." (PMID 40431659, 2025). "To identify the role of TRIM38, TRIM21, and TRIM14 proteins during flavivirus infection, we made polyclonal A549 cells overexpressing these TRIMs." (PMID 40431659, 2025).
kidney cancer (1 paper, 2020). Primary or metastatic malignant neoplasm involving the kidney. "The expression levels of TRIM14, PML, and TRIM21 were significantly higher in kidney cancer tissues than in normal tissues." (PMID 33173411, 2020).
Oral leukoplakia (1 paper, 2024). A thickened white patch on the oral mucosa that cannot be rubbed off. "It has been reported that high expression of TRIM14 in oral leukuplakia in oral leukoplakia is associated with an increased risk of progression to OSCC." (PMID 39719450, 2024). "Consequently, TRIM14 could serve as a biomarker for the malignant transformation of oral leucoplakia, and its inhibition may improve OSCC treatment outcomes." (PMID 39719450, 2024). "In addition, circRNA hsa_circ_0060927 may upregulate TRIM14 by sponging miR-195-5p, which in turn promotes the conversion of oral leukoplakia to OSCC." (PMID 39719450, 2024).
ZIKV infection (1 paper, 2025). "Further characterizations showed that TRIM21 and TRIM14 act as restriction factors against ZIKV and LGTV, while TRIM38 hinders ZIKV infection." (PMID 40431659, 2025). "While it is novel and insightful to identify TRIM21 and TRIM14 as antiviral factors during LGTV and ZIKV infection, we acknowledge certain limitations in our findings." (PMID 40431659, 2025).
tumor (26 papers, 2016 to 2025). "In this study, xenografted tumors from TRIM14-deficient cells gave rise to faster tumor growth with markedly reduced apoptotic cells compared to its isogenic controls at necropsy." (PMID 28059079, 2017). "Conversely, tumors formed by TRIM14-deficient cells (H1650 and H157) exhibited increased tumor growth rates and greater tumor weights than control tumors." (PMID 28059079, 2017). "Expression of TRIM14 was significantly associated with higher tumor stage (P = 0.038) and histologic grade (P = 0.012)." (PMID 28205534, 2017). "Tripartite motif containing 14 (TRIM14) has been reported to play a critical role in tumor development and high levels of TRIM14 are associated with poor prognosis in HCCpatients,and downregulation of TRIM14 could be beneficial in JS-K antitumor effects." (PMID 34001947, 2021). "In addition, differences in apoptotic activity between TRIM14-deficient and control tumors suggests that TRIM14 tumor suppressor activity may depend on cell death signaling pathways." (PMID 28059079, 2017). "The results showed that TRIM14 expression in primary GBM tumor samples was significantly higher than in normal brain tissue (p < 0.001)." (PMID 41463095, 2025). "Further stratified analysis revealed that TRIM14 expression was elevated in tumor patients of different ethnicities and genders compared to normal tissue (p < 0.05, p < 0.01, p < 0.001), suggesting that this upregulation is widespread." (PMID 41463095, 2025). "In vivo, orthotopic implantation of HGC-27/OXA cells into SCID-Beige mice showed that TRIM14 promoted tumor growth." (PMID 39768197, 2024). "In contrast with the vector group, TRIM14 overexpression greatly decreased E-cadherin expression and upregulated the profiles of N-cadherin, Snail, and Vimentin in the tumor tissues (p < 0.05)." (PMID 37628777, 2023). "As shown by the data, TRIM14 level was notably higher in the tumor tissues of HCC patients than in the adjacent tissues." (PMID 37628777, 2023). "In comparison with the Si-NC group, TRIM14 knockdown decreased the percentages of positive TRIM14 and Vimentin cells in the tumor cells." (PMID 37628777, 2023). "In comparison with the vector group, the tumor volume and mass of the mice overexpressing TRIM14 were apparently augmented (p < 0.05)." (PMID 37628777, 2023). "As exhibited by immunohistochemistry, in contrast with the vector group, the TRIM14 overexpression group had a higher expression of TRIM14, Vimentin, and N-cadherin in the tumor, while E-cadherin was repressed following TRIM14 overexpression." (PMID 37628777, 2023). "Previous studies have reported that TRIM14 acted as an oncogene in many cancers and participated in regulating tumor malignancy." (PMID 33982666, 2021). "Of these, DHRS3, DUSP4, GAN, RGS12, and TRIM14 are known oncogenes or tumor suppressors (as indicated by CancerMine)." (PMID 33849068, 2021). "Most importantly, we demonstrated that MSC-AS1 influenced the tumor progression by regulating miR-325/TRIM14 axis in CRC." (PMID 34054957, 2021). "Above all, we demonstrated that MSC-AS1 promoted tumor progression by sponging miR-325 to increase TRIM14 expression in CRC." (PMID 34054957, 2021). "Overexpression of TRIM14 in CRC cells via increased STAT3 phosphorylation induced the expression of tumor relevant target genes of STAT3 including MMP-2, MMP-9 and vascular endothelial derived growth factor (VEGF)." (PMID 33066016, 2020). "Our findings suggest that miR-195-5p works as a tumor suppressor by downregulating the expression of TRIM14 in OSCC." (PMID 29204446, 2017). "Secondly, silencing of TRIM14 expression significantly enhanced tumor growth in NSCLC xenograft mouse models, while exogenous TRIM14 expression attenuated tumorigenesis." (PMID 28059079, 2017). "The tumor suppressive function of TRIM14 was subsequently confirmed in several NSCLC cell line models both in vitro and in vivo." (PMID 28059079, 2017).
tumor (continued). "Our functional data therefore establish a novel tumor suppressive role for TRIM14 in NSCLC progression." (PMID 28059079, 2017). "Our results provide new insights into the pathogenesis of NSCLC and highlight TRIM14 as a potential tumor suppressor and regulator of innate immune response in NSCLC cells." (PMID 28059079, 2017). "Overexpression of TRIM14 significantly attenuated tumor growth in H3255 xenograft models (p = 0.0021)." (PMID 28059079, 2017). "The biological effects of TRIM14 overexpression on TSCC progression were further examined using a xenograft tumor model." (PMID 26799420, 2016). "In in vivo experiments, TRIM14 upregulation bolstered tumor growth." (PMID 37628777, 2023). "A xenograft tumor model was used to confirm the impact of TRIM14 on tumor cell growth." (PMID 37628777, 2023). "Further rescue experiments were performed to verify whether GAS6-AS1 promoted tumor progression in a TRIM14-dependent manner." (PMID 35962353, 2022). "Overexpression of TRIM14 promoted tumor cells proliferation and invasion through the AKT pathway." (PMID 33982666, 2021). "Collectively, our findings support the notion that TRIM14 may be acting via apoptotic/cell death pathways to exert its tumor suppressive phenotype." (PMID 28059079, 2017). "Therefore, we reason that the tumor suppressor role of miR-195-5p in OSCC is dependent on the interaction with TRIM14." (PMID 29204446, 2017). "Furthermore, comparative analyses showed that TRIM14 expression were elevated in the ten TSCC samples compared with matched adjacent non-tumor tissues, suggesting that TRIM14 is upregulated in human TSCC." (PMID 26799420, 2016). "Moreover, through RNA sequencing analysis in tumor CD8+ T cells, we found that genes associated with effector functions, such as Sox6, Ccnd1, CD81 and Trim14, were upregulated, while genes associated with immune inhibition, such as Tox, Jun-b, Btla, Batf and Foxp1 were downregulated 25-27." (PMID 38994031, 2024). "And Targeting TRIM14 may improve the tumor microenvironment of EC and delay the progression." (PMID 39719450, 2024). "Moreover, repressing STAT3 and HIF-1α could mitigate the tumor-promoting role of TRIM14 in HCC cells." (PMID 37628777, 2023). "Furthermore, overexpressed TRIM14 also promoted tumor cells epithelial-mesenchymal transition." (PMID 33982666, 2021). "Moreover, Western blot analyses on tumor lysates confirmed sustained silencing of TRIM14 protein levels in H1650 during tumor progression, which coincided with reduced protein expression of apoptosis-inducing factor (AIF), another caspase-independent apoptotic pathway." (PMID 28059079, 2017). "In our experiments, TRIM14 overexpression promoted the upregulation of ATP7A, enhancing copper efflux in tumor cells." (PMID 41463095, 2025). "TRIM14 then interacts with NEMO to release NF-κB by phosphorylation of IκBα via classical IKK complex, activating the NF-κB pathway and promoting tumor progression." (PMID 39719450, 2024). "To confirm the function of TRIM14 in HCC cell growth in vivo, we engineered a nude mouse tumor formation model and gauged the mouse tumor volume and mass." (PMID 37628777, 2023). "In the tumor tissues, STAT3 phosphorylation was strengthened, and HIF-1A expression was distinctly upregulated in the TRIM14 overexpression group compared to the vector group (p < 0.05)." (PMID 37628777, 2023). "TRIM14 was expressed in both the cytoplasmic and membranous parts of normal liver cells and HCC tumor cells." (PMID 37628777, 2023). "Conversely, tumors formed by TRIM14-silenced TSCC cells were smaller and had lower tumor weights than control tumors." (PMID 26799420, 2016). "In this process, TRIM14 mediates the phosphorylation and activation of STAT1 after IFN-γ stimulation, and the modified STAT1 can widely improve IFN signaling, thus functioning as a tumor suppressor." (PMID 39719450, 2024). "Accordingly, inhibiting TRIM14 expression in BC and PTC may promote apoptosis and inhibit tumor progression." (PMID 39719450, 2024).